MID1 (midline 1)
Diseases named in the same sentence as MID1 in open-access papers (continued):
Sharing a sentence is not in itself a finding about the gene and the disease.
lung adenocarcinoma (4 papers, 2014 to 2021). A carcinoma that arises from the lung and is characterized by the presence of malignant glandular epithelial cells. "The transfection of lung adenocarcinoma cell lines with MID1 siRNA, upregulated PP2A expression and induced apoptosis and cell cycle arrest." (PMID 31623614, 2019). "MID1 is upregulated in LC cell lines, compared bronchial epithelial cells, and in lung adenocarcinoma tissue, compared to normal adjacent tissue." (PMID 31623614, 2019).
melanoma (4 papers, 2014 to 2020). A malignant, usually aggressive tumor composed of atypical, neoplastic melanocytes. "We used the GEPIA database to investigate the prognostic analysis of TRIM2, TRIM7, TRIM8, TRIM18 (MID1), TRIM19 (PML), TRIM27, and TRIM29 in melanoma." (PMID 33118318, 2020). "Differential expression of TRIM2, TRIM7, TRIM8, TRIM18 (MID1), TRIM19 (PML), TRIM27, and TRIM29 may play an important role in the development of melanoma." (PMID 33118318, 2020).
breast carcinoma (3 papers, 2014 to 2019). "On the contrary, down-regulation of MID1 mediated by miR-135b has been shown to promote tumour progression of mammary carcinomas." (PMID 30941058, 2019). "MID1 was recently shown to mediate the ubiquitin-dependent degradation of α4, a regulator of mTOR and cell-cycle progression, which is highly expressed in breast cancer." (PMID 24944582, 2014). "Only one miRNA, miR-135b, has been shown previously to bind the MID1 3’-UTR and regulate MID1 expression in breast cancer cells." (PMID 29293623, 2018).
diabetic kidney disease (3 papers, 2021 to 2025). Progressive kidney disorder caused by vascular damage to the glomerular capillaries, in patients with diabetes mellitus. "Midline-1 (MID1) is an E3 ubiquitin ligase belonging to Tripartite Motif family and its involvement in the initiation and progression of many diseases, such as diabetic kidney disease has been well accepted." (PMID 40206598, 2025). "In addition, one of the more recently defined Mid-1 ubiquitination targets is non-receptor tyrosine phosphatase PTP1B, whose degradation leads to overactivation of the STAT3 signaling pathway and promotes inflammation and fibrosis in diabetic kidney disease." (PMID 40443734, 2025).
pulmonary fibrosis (3 papers, 2019 to 2025). Chronic progressive interstitial lung disorder characterized by the replacement of the lung tissue by connective tissue, leading to progressive dyspnea, respiratory failure, or right heart failure. "In models of bleomycin-induced pulmonary fibrosis, increased MID1 activity and decreased PP2A activity are observed." (PMID 40901482, 2025). "The same research group reported similar results in the model of experimental allergic esophagitis, with disease amelioration in TRAIL −/− mice and proposed a disease-promoting role of Mid-1 downstream of TRAIL in the pathogenesis of pulmonary fibrosis." (PMID 40443734, 2025). "In support of the human data WT BALB/c mice with bleomycin-induced lung fibrosis displayed a marked upregulation of Mid1 and a downregulation of PP2A activity in their lungs." (PMID 30732588, 2019). "In the context of COPD and allergic airway diseases triggered by allergens such as dust mites or egg proteins, TNF-related apoptosis-inducing ligand (TRAIL) can alleviate pulmonary fibrosis by up-regulating MID1 (E3 ubiquitin ligase), which inactivates protein phosphatase 2A (PP2A)." (PMID 40901482, 2025). "We have previously demonstrated that TRAIL signalling through the ubiquitin ligase Mid1 and dysregulation of PP2A activity plays a key role in lung fibrosis in house dust mite and ovalbumin-induced allergic airways disease models." (PMID 30732588, 2019).
dementia (2 papers, 2014 to 2022). Loss of intellectual abilities interfering with an individual's social and occupational functions. "Midline 1 (Mid1), a microtubule-associated E3 ubiquitin ligase (also known as tripartite motif-containing protein 18, TRIM18) is known to be involved in organ development and diseases, such as cancer, dementia and allergic inflammation." (PMID 36614145, 2022).
experimental autoimmune encephalomyelitis (2 papers, 2024 to 2025). An autoimmune demyelinating disease of the central nervous system that is produced experimentally in animals by the injection of homogenized brain or spinal cord in Freund's adjuvant. "Recent study documented the role of Mid-1 in regulation of T cell entrance to the CNS in a model of experimental autoimmune encephalomyelitis and the ability of Mid-1 to affect mTOR signaling in T lymphocytes." (PMID 40443734, 2025). "Here we reported that midline-1 (Mid1) is a key regulator of effector T cell migration in experimental autoimmune encephalomyelitis (EAE), a widely used animal model of MS." (PMID 38323310, 2024).
myocarditis (2 papers, 2022 to 2023). Myocarditis is a condition that is characterized by inflammation of the heart muscle (myocardium). "Using this model, investigators recently showed that an X-linked gene Midline 1/Md1 that regulates TRIM18 expression reduces type I interferon levels in male C57BL/6 mice in response to CVB3 infection altering survival and myocarditis." (PMID 36937911, 2023).
osteoarthritis (2 papers, 2020 to 2025). A noninflammatory degenerative joint disease occurring chiefly in older persons, characterized by degeneration of the articular cartilage, hypertrophy of bone at the margins and changes in the synovial membrane. "Interestingly, by mining a published microarray database (GSE57218), we found that IFN-related genes (STAT1, IFNGR2, NCAM1, MID1) were highly elevated in the cartilage tissues of osteoarthritis patients." (PMID 32202492, 2020). "On the other hand, Mid-1 ubiquitinates RIC8 guanine nucleotide exchange factor A, which promotes the progression of osteoarthritis by activating p38 mitogen-activated protein kinase signaling pathway in chondrocytes, thus pointing to a protective effect of Mid-1 signaling in OA." (PMID 40443734, 2025).
Sepsis (2 papers, 2022 to 2025). Sepsis is defined as life-threatening organ dysfunction caused by a dysregulated host response to infection. "It was found that TNF-α challenge elevated Mid1 expression more than 5-fold compared with unstimulated samples, indicating that endothelial cell expression of Mid1 is increased in response to both sepsis and TNF-α exposure." (PMID 36614145, 2022). "However, the role of Mid1 in regulating endothelial cell expression of ICAM-1 and neutrophil adhesion during sepsis has not been investigated." (PMID 36614145, 2022).
tauopathies (2 papers, 2017 to 2021). "Taken together, although the role of Mid1 in pathological alterations of tau in the in vivo brain remains to be elucidated, the results of the present study provide novel insight into the mechanism underlying the pathological alterations of tau in tauopathy." (PMID 33953293, 2021). "Our data suggest a key role of MID1 in the pathology of AD and related tauopathies." (PMID 29062069, 2017).
acrocallosal syndrome (1 paper, 2009). Acrocallosal syndrome (ACS) is a polymalformative syndrome characterized by agenesis of corpus callosum (CC), distal anomalies of limbs, minor craniofacial anomalies and intellectual deficit. "Furthermore, we show that missense mutations in this region, as observed in GCPS and acrocallosal syndrome patients, lead to changes in the subcellular localization of the GLI3 protein and interfere with its regulation by the MID1-α4-PP2A complex." (PMID 19829694, 2009). "Interestingly, some GCPS point mutations and a mutation in a patient with acrocallosal syndrome are located in the identified MID1-α4-PP2A complex-dependent regulation domain of GLI3 [A943P (as found in one patient with acrocallosal syndrome), I808M and P707S (as found in GCPS patients)]." (PMID 19829694, 2009). "Interestingly, the three GLI3-related conditions GCPS, PHS and acrocallosal syndrome show phenotypic overlap with Opitz BBB/G syndrome (OS [MIM300000 and 145410]), a midline malformation syndrome caused by loss-of-function mutations of MID1." (PMID 19829694, 2009).
allergic disease (1 paper, 2023). An immune response that occurs following re-exposure to an innocuous antigen, and that requires the presence of existing antibodies against that antigen. "Our previous studies comprehensively outlined the role of TRAIL and MID-1 signalling axis in the propagation of allergic diseases of the airways and EoE models." (PMID 38026128, 2023).
androgen insensitivity syndrome (1 paper, 2014). Androgen insensitivity syndrome (AIS) is a disorder of sex development (DSD) characterized by the presence of female external genitalia, ambiguous genitalia or variable defects in virilization in a 46,XY individual with absent or partial responsiveness to age-appropriate levels of androgens. "These urogenital malformations resemble those of patients with partial androgen insensitivity syndrome, suggesting a link between MID1 and androgen signaling." (PMID 24913494, 2014).
Arthritis (1 paper, 2025). Inflammation of a joint. "Among them, Mid1 had the strongest association with inflammation markers and its expression was clearly upregulated with the onset of arthritis, suggesting its involvement in the pathogenesis of AIA." (PMID 40443734, 2025). "Mid-1 aids in an inflammatory polarization of myeloid cells and promotes bone loss and cartilage degradation in arthritis." (PMID 40443734, 2025). "Mid1 enhances inflammatory polarization of myeloid cells and promotes bone and cartilage degradation in arthritis." (PMID 40443734, 2025). "Expression levels of Erdr1 were similar in NI and AIA wt mice while Mid1 was upregulated in wt AIA mice in comparison to the NI group, which pointed to its potential association with arthritis pathogenesis." (PMID 40443734, 2025). "We further assessed the effect of Mid1 inactivation on arthritis in Mid1 −/− mice." (PMID 40443734, 2025). "The discrepancies between the results could be ascribed to differences in arthritis model, as well as to different approaches to induce Mid1 deletion, so additional mechanistic studies are required to resolve these issues." (PMID 40443734, 2025). "In addition, a recent study reported complete protection of Mid1 −/− mice from development of collagen-induced arthritis." (PMID 40443734, 2025). "Mid1 −/− mice developed AIA but joint swelling and arthritis visual score were reduced in comparison to wt AIA mice." (PMID 40443734, 2025).
atherosclerosis (1 paper, 2023). A disease characterized by the build-up of fatty material and calcium deposition in the arterial wall resulting in partial or complete occlusion of the arterial lumen. "In this study, we reported a previously unrecognized role of DPP4 in atherosclerosis associated inflammation though regulation of T‐cell migration via Mid1, a microtubule‐associated protein." (PMID 36683148, 2023). "DPP4 controls T‐cell migration by regulating Mid1‐dependent cytoskeletal rearrangement, and thus promotes vascular inflammation in atherosclerosis." (PMID 36683148, 2023). "Collectively, we demonstrate that T‐cell derived DPP4 plays an important role in atherosclerosis by regulating Mid1‐mediated migration." (PMID 36683148, 2023). "Thus, DPP4/Mid1, as a novel regulator of T‐cell motility, may be a potential inflammatory target in atherosclerosis." (PMID 36683148, 2023).
autoimmune disease (1 paper, 2024). A disorder resulting from loss of function or tissue destruction of an organ or multiple organs, arising from humoral or cellular immune responses of the individual to their own tissue constituents. "However, it remains unclear as to the level that Mid1 is involved in autoimmune disease." (PMID 38323310, 2024).
campomelic dysplasia (1 paper, 2024). "Potentially pathogenic variants were discovered in the FAS and pFAS groups, including those known to cause craniofacial malformations, such as SOX9 (Campomelic Dysplasia), STRA6 (Matthew–Wood), CHD7 (CHARGE), MID1 and MED15 (Opitz–Kaveggia syndrome), and several 22q11.2DS genes." (PMID 38785976, 2024).
Cognitive impairment (1 paper, 2026). Abnormal cognition is characterized by deficits in thinking, reasoning, or remembering.
congenital brain malformations (1 paper, 2016). "Based on their de novo occurrence and/or their established association with congenital brain malformations, we detected five disease-causing CNVs in four fetuses involving chromosomal regions 6p25.1-6p25.3 (FOXC1), 6q27, 16p12.3, Xp22.2-Xp22.32 (MID1), and Xp22.32-Xp22.33." (PMID 27087860, 2016).
eosinophilia (1 paper, 2023). "Furthermore, MID-1 siRNA ablated both eotaxin-1 expression and eosinophilia after rIL-13 administration, which indicative that IL-13 induces eosinophilic infiltration through MID-1 signaling." (PMID 38026128, 2023). "IL-13-driven eosinophil infiltration of the esophagus induced eosinophilia and eotaxin-1 expression in a STAT6-dependent and MID-1-dependent manner." (PMID 38026128, 2023). "We demonstrate that IL-13-mediated eosinophil infiltration depends on TRAIL and MID-1 and that MID-1-knockdown completely ablated eosinophilia and eotaxin-1 production, unlike TRAIL deficiency." (PMID 38026128, 2023).
epilepsy (1 paper, 2024). A brain disorder characterized by episodes of abnormally increased neuronal discharge resulting in transient episodes of sensory or motor neurological dysfunction, or psychic dysfunction. "Among the triplosensitive genes located in the duplicated region, ARX, CDKL5, CNKSR2, MID1, PTCHD1, RPS6KA3, and SMS are known to be involved in intellectual developmental disorders with/without epilepsy." (PMID 39062680, 2024).
lobular carcinomas (1 paper, 2007). "Overexpressed genes in lobular carcinomas were the tumor suppressor FOXP1 and another transcription regulator MID1." (PMID 17389037, 2007).
lung carcinoma (1 paper, 2015). "In turn, the Xq22 region harbors several putative tumors suppressor genes which are inactivated by mutations in lung cancer cell lines and primary tumors (i.e. GRPR, VEGFD,and MID1)." (PMID 25415227, 2015).
neuroblastoma (1 paper, 2022). Neuroblastoma (NB) is the most common solid, extracranial childhood tumor. "Therefore, we tested the effects of overexpressing Mid1 on the level of pathogenic AR protein in the mouse Neuroblastoma-Spinal Cord hybrid (NSC) 34 cell line." (PMID 35821212, 2022).
spinocerebellar ataxia type 2 (1 paper, 2021). A subtype of type I autosomal dominant cerebellar ataxia (ADCA type I) characterized by truncal ataxia, dysarthria, slowed saccades and less commonly ophthalmoparesis and chorea. "Interestingly, MID1 binds to multiple CAG-repeat mRNAs regardless of the repeat-flanking sequences so that translation induction by MID1 occurs in cell models of multiple CAG-repeat diseases, such as HD and spinocerebellar ataxia types 2 (SCA2), 3 (SCA3) and 7 (SCA7)." (PMID 34357961, 2021).
systemic lupus erythematosus (1 paper, 2015). An autoimmune multi-organ disease typically associated with vasculopathy and autoantibody production. "It has also been described for HERV-E.FABP7 in leukemic B cells; HERV-E.PTN, HERV-E.EDNRB, and HERV-E.MID1 in placenta but not in blood cells; and HERV-E clone 4-1 in peripheral blood lymphocytes (CD4+, CD8+ and B cells) but not in neutrophils from patients with systemic lupus erythematosus (SLE)." (PMID 25785516, 2015).
tricuspid valve insufficiency (1 paper, 2020). The backflow of blood from the right ventricle into the right atrium, owning to imperfect functioning/insufficiency of the tricuspid valve. "A frameshift variant in MID1 was identified in an ARM-PLUS patient with perineal fistula, tricuspid valve insufficiency, and hypospadia (ID = 6)." (PMID 32656166, 2020).
cancer (11 papers, 2009 to 2025). A tumor composed of atypical neoplastic, often pleomorphic cells that invade other tissues. "MID1, a microtubule-associated ubiquitin E3 ligase, has been reported to play an important role in cancer." (PMID 35004288, 2021). "Misregulation of MID1 expression is associated with various diseases including midline malformation syndromes, cancer and neurodegenerative diseases." (PMID 29293623, 2018). "In the adult, however, abnormal MID1 function has been associated with neurodegenerative diseases as well as cancer." (PMID 29293623, 2018). "Additionally, MID1 regulates processes that are linked to carcinogenesis and an abnormal activity of MID1 has been shown in different cancer cell types." (PMID 29293623, 2018). "Besides its role in OS MID1 function has been associated with the development and progression of various other diseases including cancer and neurodegenerative diseases." (PMID 29293623, 2018). "MID1 expression level was significantly increased not only in cancer compared to benign but also increased in high compared to low Gleason score tumors." (PMID 24913494, 2014). "The awareness of MID1 as an essential regulator of a pool of specific mRNAs involved in cancer development and progression is a novel concept." (PMID 24913494, 2014). "We have recently shown that the subcellular localization and transcriptional activity of GLI3 is regulated by PP2A activity and the MID1-α4 ubiquitin ligase complex in several cancer cell lines with autonomously activated SHH-signaling." (PMID 19829694, 2009). "Future studies should investigate whether a downregulation of these miRNAs is functionally connected to an upregulation of MID1 in these cancers." (PMID 29293623, 2018). "Mimics of miRNAs that target MID1 could be promising miRNA therapeutics to treat cancer as well as neurodegenerative diseases." (PMID 29293623, 2018). "MID1 is overexpressed in certain cancer types and promotes cancer growth." (PMID 29293623, 2018). "In conclusion, these findings identify MID1 as an interesting novel upstream modulator of proliferating pathways and as an important regulatory hub in tumor cells, making it a promising target for anti-cancer drug development." (PMID 24913494, 2014). "The target protein of Mid1 is protein phosphatase 2A (PP2A) complex and levels of PP2A has been shown to regulate cancer cell proliferation, migration, cytoskeletal rearrangement and apoptosis." (PMID 36614145, 2022). "The previous studies using PLATO have identified a set of TRIM proteins (TRIM1/MID2, TRIM18/MID1, TRIM54 and TRIM55) as cancer autoantigens of paraneoplastic neurological disorder (PND)." (PMID 31494268, 2019). "When the cancer samples were categorized to cribriform and non-cribriform sets, MID1 expression level was significantly higher in the cribriform sample set." (PMID 24913494, 2014).